RN7SKP135 (RN7SK pseudogene 135)
Gene: Miscellaneous RNA gene on chromosome 8 (63,609,354 to 63,609,600, reverse strand). Ensembl gene ENSG00000252358.
Homologues: Orthologues: chimpanzee 7SK (60% identical). Paralogues in human: RN7SKP180 (56% identical), RN7SKP189 (56% identical), RN7SKP79 (56% identical), RN7SKP9 (56% identical), 7SK (56% identical), RN7SKP20 (56% identical), RN7SKP204 (56% identical), RN7SKP211 (56% identical), RN7SKP118 (55% identical), RN7SKP128 (55% identical), RN7SKP151 (55% identical), RN7SKP176 (55% identical), and 283 more.